PAX5 (paired box 5)
Description:
Transcription factor that plays an essential role in commitment of lymphoid progenitors to the B-lymphocyte lineage. Fulfills a dual role by repressing B-lineage inappropriate genes and simultaneously activating B-lineage-specific genes. In turn, regulates cell adhesion and migration, induces V(H)-to-D(H)J(H) recombination, facilitates pre-B-cell receptor signaling and promotes development to the mature B-cell stage. Repression of the cohesin-release factor WAPL causes global changes of the chromosomal architecture in pro-B cells to facilitate the generation of a diverse antibody repertoire. (Microbial infection) Plays an essential role in the maintenance of Epstein-Barr virus genome copy number within the host cell by promoting EBNA1/oriP-dependent binding and transcription. Also participates in the inhibition of lytic EBV reactivation by modulating viral BZLF1 activity.
Synonyms: BSAP; PAX-5; ALL3
Tractability: Small molecule: it has a binding pocket of medium quality. PROTAC: its protein half-life has been measured.
Gene: Protein-coding gene on chromosome 9 (36,833,269 to 37,034,268, reverse strand). Ensembl gene ENSG00000196092.
Subcellular location: Nucleus
Subcellular location (Human Protein Atlas): Nucleoplasm
Pathways (Reactome):
Gene expression (Transcription): RUNX1 regulates transcription of genes involved in BCR signaling
Gene Ontology:
Molecular function: protein binding; DNA-binding transcription factor activity, RNA polymerase II-specific; RNA polymerase II cis-regulatory region sequence-specific DNA binding; DNA binding; DNA-binding transcription activator activity, RNA polymerase II-specific; DNA-binding transcription factor activity
Biological process: B cell differentiation; nervous system development; regulation of transcription by RNA polymerase II; sensory organ development; transcription by RNA polymerase II; cell differentiation; positive regulation of transcription by RNA polymerase II; regulation of DNA-templated transcription
Cellular component: nucleoplasm; nucleus; chromatin
Genetic constraint (gnomAD): Loss-of-function variants: 8 observed, 40.01 expected, observed/expected ratio (o/e) 0.2, 90% interval 0.12 to 0.36. The upper end of that interval is the gene's LOEUF score, 0.36, which puts it in group 1 of 6, group 1 being the genes least tolerant of losing a copy. Missense variants: 373 observed, 521.64 expected, observed/expected ratio (o/e) 0.72, 90% interval 0.66 to 0.78. Synonymous variants: 224 observed, 215.49 expected, observed/expected ratio (o/e) 1.04, 90% interval 0.93 to 1.16.
Gene-disease validity (ClinGen):
ClinGen rates the evidence that PAX5 causes each of these diseases.
leukemia, acute lymphoblastic, susceptibility to, 3 (autosomal dominant): Definitive. Any precursor B-cell acute lymphoblastic leukemia in which the cause of the disease is a mutation in the PAX5 gene.
Cancer hallmarks: escaping programmed cell death; escaping programmed cell death (suppresses); proliferative signalling (promotes); invasion and metastasis (promotes)
Homologues: Orthologues: chimpanzee PAX5 (100% identical), guinea pig PAX5 (99% identical), mouse Pax5 (99% identical), rat Pax5 (99% identical), dog PAX5 (99% identical), rabbit PAX5 (94% identical), tropical clawed frog pax5 (92% identical), pig PAX5 (91% identical), zebrafish pax5 (75% identical), macaque PAX5 (69% identical). Paralogues in human: PAX2 (72% identical), PAX8 (59% identical), PAX3 (41% identical), PAX7 (41% identical), PAX9 (36% identical), PAX1 (35% identical), PAX4 (27% identical), PAX6 (17% identical), ARX (14% identical), UNCX (14% identical), EVX2 (13% identical), NOBOX (12% identical), and 38 more.
Diseases named in the same sentence as PAX5 in open-access papers:
PAX5 is named in the same sentence as 195 diseases in open-access papers, as found by Europe PMC text mining. Sharing a sentence is not in itself a finding about the gene and the disease. The quoted sentences say what the papers report.
leukemia (86 papers, 2006 to 2025). A malignant (clonal) hematologic disorder, involving hematopoietic stem cells and characterized by the presence of primitive or atypical myeloid or lymphoid cells in the bone marrow and the blood. "In line with existing literature, familial segregation of the PAX5 variant demonstrated high but incomplete penetrance, as two leukemia‐free mutation carriers displayed only subclinical B lymphocyte maturation abnormalities without hypogammaglobulinemia." (PMID 40981401, 2025). "All these mouse B-ALLs lacked surface CD19 expression, in agreement with the loss of or marked reduction in Pax5 activity, similar to what is found in human leukemia." (PMID 41283237, 2025). "WES identified four mutations at the Pax5 locus, as well as other leukemia hotspot mutations such as Nras:p.Q61H and Jak3:p.R653H." (PMID 41283237, 2025). "This is key for early therapy or even prevention in both, PAX5-mediated familial BCP-ALL predisposition and somatically acquired PAX5-driven leukemias." (PMID 40394211, 2025). "PAX5 is found to be involved in several leukemia-associated rearrangements, resulting in the fusion genes encoding chimeric proteins that antagonize PAX5 transcriptional activity." (PMID 39408690, 2024). "The introduction of targeted pax5 and cdkn2a/b gene mutations, mimicking secondary mutations, in the E::R line significantly increased the incidence in leukemia." (PMID 38136366, 2023). "Functional studies showed that PAX5 p.Arg38His is also a hypomorphic variant resulting in incomplete B-cell differentiation and is sufficient to predispose to leukemia." (PMID 37543654, 2023). "Similar to leukemias from the delayed Pax5+/− group, early exposure tumors showed recurrent mutations affecting the remaining WT Pax5 allele, with Pax5 p.P80R occurring in 2 out of 4 analyzed leukemias." (PMID 37620322, 2023). "Collectively, these observations revealed that downregulation of Myd88 is associated with increased development of leukemia with a similar genetic profile as the leukemias observed in Pax5+/− mice and those from human patients." (PMID 37620322, 2023). "This proof-of-principle experiment has been conducted in a mouse model that recapitulates the phenotype of a leukemia-predisposition syndrome (Pax5+/- mice) that develop B-ALL upon exposure to common infections." (PMID 37901253, 2023). "In the leukemia of the affected family members a second somatic alteration was detected in PAX5, either by loss of heterozygosity (LOH) or a second somatic mutation." (PMID 37543654, 2023). "We used the Integrative Genomics Viewer (IGV) to analyze the mapped reads from the leukemia transcriptomes, confirming that the leukemic fish had deleterious mutations in exon 3 and exon 5 of the pax5 gene." (PMID 38136366, 2023). "The strong selection for loss of heterozygosity identified Pax5‐Jak2 as a nuclear oncoprotein and important driver of leukemia development, which functions by maintaining high levels of phosphorylated STAT5 in the nucleus." (PMID 35156727, 2022). "The DNA‐binding function and kinase activity of Pax5‐Jak2 both contributed to leukemia development, as evidenced by mutation of the paired domain of Pax5 or the catalytic center of Jak2." (PMID 35156727, 2022). "Regarding the role of Pax5, pro-B cells from Pax5 deficient mice had increased glucose uptake and energy metabolism, with upregulation of metabolic genes, as seen for human leukemia." (PMID 35216407, 2022). "The leukemias with the next highest relative ELP signals were PAX5 and MEF2D-mutated B-ALL, although the ELP signals there were accompanied by stronger signals from later B-cell stages." (PMID 35288693, 2022). "We have seen the role played in leukemia development by inherited mutations affecting the Pax5 locus." (PMID 35886910, 2022). "Copy number analyses and exome sequencing of leukemia samples revealed that 30% harbored inactivating mutations or deletion of Pax5 that resulted in decreased expression." (PMID 34484175, 2021).
leukemia (continued). "Under the same conditions, ETV6-RUNX1 expressed in hematopoietic progenitors readily induces leukemia if the mice are kept in a natural infection environment or if a second mutation (Kdm5c or Pax5 loss) occurs in close succession." (PMID 34336858, 2021). "Given the observed upregulation of IL-6 in Pax5-deficient leukemic proB cells and mice, we next directly tested the requirement for IL-6 in Pax5-loss mediated leukemia growth in a system that recapitulates the spontaneous process of leukemogenesis." (PMID 33154497, 2020). "Our data reveals that PAX5 belong to a regulatory network frequently targeted by multiple mutations in B-ALL shedding light on the molecular interplay in leukemia cells." (PMID 31381561, 2019). "WGS studies identified non‐coding recurrent mutations, including the 3′‐UTR of NOTCH1 and a PAX5 enhancer, resulting in significant activity alterations of these transcription factors genes of well‐known importance in leukemia and other malignancies." (PMID 30520556, 2019). "Even though inherited point mutations in PAX5 have been reported to result in increased leukemia incidence, the reduced functional TF activity more commonly depends on the inactivation of the TF genes via somatic heterozygote mutations and deletions." (PMID 29966360, 2018). "While the variable penetrance of BCP-ALL in these families can be explained by additional environmental influences, as previously shown by our group through infection exposures, the initial effect of PAX5-mediated leukemia predisposition is insufficiently understood." (PMID 40394211, 2025). "Overall, the same genes appear mutated in Pax5+/− murine leukemias as in human B-ALL samples." (PMID 41283237, 2025). "Thus, we have utilized the Pax5+/− leukemia-prone model to investigate the mechanisms underlying immune evasion during progression to B-ALL." (PMID 41283237, 2025). "In contrast, PD-1 was upregulated upon the conversion to leukemic B cells in the BM, defined by the lack of CD19 expression in parallel with their emergence in the peripheral blood (PB), indicating a loss of or marked reduction in Pax5 activity similar to what is found in human leukemia." (PMID 41283237, 2025). "Beyond these molecular aspects, extending knowledge about cancer penetrance and long‐term outcomes in PAX5 mutation carriers may enable the development of effective surveillance strategies for this leukemia predisposing syndrome." (PMID 40981401, 2025). "In addition PAX5-variant-related leukemia is commonly associated with aberrant activation of the kinase pathways such as JAK/STAT and RAS signaling." (PMID 36387144, 2022). "Therefore, the Pax5+/− model has been instrumental to deciphering the associations between genetic predisposition to leukemia and environmental factors." (PMID 35886910, 2022). "Analysis of mouse leukemia from the Pax5 P80R heterozygous mice revealed the disruption of the remaining Pax5 WT allele by deletion or frameshift mutations, which recapitulated the loss of PAX5 WT allele in patient samples." (PMID 36387144, 2022). "However, different to most other B‐ALLs, loss of the wild‐type Pax5 allele is a genetic alteration leading to accelerated leukemia development in Pax5Jak2/+ mice." (PMID 35156727, 2022). "In addition to mice mutated in Pax5 or Ikzf1, Irf4/Irf8−/−, and Irf4/Spi1−/− mice have been shown to develop leukemia early in life at a high incidence." (PMID 35459909, 2022).
leukemia (continued). "Recent large-scale genomic analyses of B-ALL have identified multiple novel subtypes driven by PAX5 genetic lesions, such as the one defined by a distinct gene expression profile and PAX5 P80R mutation, which is an exemplar leukemia entity driven by a missense mutation." (PMID 36387144, 2022). "To investigate whether the loss of Pax5 is a prerequisite for leukemia formation, we reasoned that ectopic transcription of Pax5 from a heterologous locus may maintain Pax5 expression in B cells of Pax5Jak2/+ mice." (PMID 35156727, 2022). "Notably, PAX5 can be labeled a “promiscuous” gene since over 16 partner genes have been identified in leukemia-associated rearrangements." (PMID 30563523, 2018). "Hence, deregulated PAX5 expression has major implications in physiologic hematopoiesis and poses a high risk for leukemia development, with somatic alterations being one of the most common features present in B-cell precursor acute lymphoblastic leukemia (BCP-ALL)." (PMID 40394211, 2025). "However, it has been demonstrated that secondary alterations involving other signaling pathways, such as JAK–STAT or RAS, may also lead to leukemia development in germline PAX5 mutation carriers." (PMID 40981401, 2025). "Moreover, an activating Jak1 p.F837V variant was identified in one of the leukemic samples, which again highlights the importance of the JAK/STAT-signaling pathway in Pax5+/− leukemias, as shown for Jak1 and Jak3 mutations in the Pax5+/− delayed-exposure B-ALL3,25." (PMID 37620322, 2023). "Notably, mature B cells upon conditional loss of Pax5 cannot only be converted into functional T cells via dedifferentiation to uncommitted bone marrow progenitor cells, but also give rise to an aggressive progenitor cell leukemia." (PMID 35156727, 2022). "However, on the other hand, genomic analysis of Pax5+/− mice subjected to mutagenesis identified secondary genetic alterations that recapitulate those observed in human leukemia, as is the case of secondary alterations of Pax5 or recurrent mutations in genes such as Jak1, Jak3, Ptpn11, and Nras." (PMID 35886910, 2022). "Secondary mutations in other genes (paired box 5/PAX5, cyclin-dependent kinase inhibitor 2A/CDKN2A, etc.)are postulated to be requisite for the full development of leukemia, and together they accelerate the onset and progression of leukemia." (PMID 40584293, 2025). "Mice heterozygous for Pax5, when exposed to infections, recapitulate the preleukemia-to-leukemia progression found in humans harboring the heterozygous germline PAX5 c.547G>A pathogenic variant." (PMID 41283237, 2025). "Downregulation of Pax5 and upregulation of Myc was validated via qRT-PCR analysis in 2 additional independent Pax5± pre-leukemic mice (pre-leukemia 5 and 7) displaying the c-KIT+ CD25+ cell population." (PMID 40394211, 2025). "This is phenocopied in the B-ALLs developing in the Pax5+/− mouse model, thus demonstrating the importance of the biallelic alterations of PAX5 for leukemia progression in this B-ALL subgroup." (PMID 41283237, 2025). "Methods and Results: Here, we identify the upregulation of PD-1 expression in preleukemic cells, triggered by Pax5 inactivation in mice and correlating with the time of conversion to leukemia, as a novel marker that favors leukemia evasion." (PMID 41283237, 2025). "Although the importance of Pax5 for B lymphopoiesis and human leukemia is well established, the mechanisms that control Pax5 biology and dynamics are still unclear." (PMID 39424985, 2024). "To identify the somatically acquired second hits leading to leukemia development, we next performed whole exome sequencing of four Pax5+/− early exposure tumors and their corresponding germline." (PMID 37620322, 2023). "PAX5 fusion genes prevent the transcription of the PAX5 gene, making it an essential target gene for the study of leukemia progression and the diagnosis of B-ALL." (PMID 37335685, 2023).
leukemia (continued). "Short-term administration of the Jak1/2 inhibitor ruxolitinib to Pax5+/− mice substantially decreases the likelihood of leukemia development by reducing the population of preleukemic cells." (PMID 37901253, 2023). "Early induction of Myd88-independent Toll-like receptor 3 signaling results in a significant delay of leukemia development in Pax5+/− mice." (PMID 37620322, 2023). "The advent of leukemia in Pax5+/−;Myd88+/− mice under natural infection exposure occurred at between 7 and 20 months of age, similar to the Pax5+/− group." (PMID 37620322, 2023). "We therefore selected BCP-ALL patients that were tested positive for PAX5 deletions in the leukemia samples and screened for these deletions in remission samples of the same patients." (PMID 37543654, 2023). "In contrast, the latency to leukemia in Pax5+/−mice treated with poly(I:C) was significantly longer than in the Pax5+/−control group receiving vehicle, where it was delayed until 12–21 months of age (p = 0.0019)." (PMID 37620322, 2023). "Increased frequency of PAX5 deletions is consistent with a later block in B-cell differentiation in Late-Pro leukemias." (PMID 37337105, 2023). "Our results show that leukemia incidence is significantly increased by secondary lesions in the pax5 and cdkn2a/b genes." (PMID 38136366, 2023). "In summary, we obtained in vivo evidence showing that Pax5+/− mice exposed to infections early in life develop leukemia with similar incidence, latency, and molecular features as Pax5+/− mice exposed later in life." (PMID 37620322, 2023). "Genetic reduction of Myd88 expression leads to a significant increase in leukemia incidence in Pax5+/−Myd88+/− mice through an inflammation-dependent mechanism." (PMID 37620322, 2023). "Here we show that dysregulation of innate immunity plays a driving role in the clonal evolution of pre-malignant Pax5+/− B-cell precursors toward leukemia." (PMID 37620322, 2023). "The co-existence of PAX5, CDKN2A, and IKZF1 mutations classifies this leukemia as “Ikaros plus” high-risk ALL30." (PMID 35115489, 2022). "As the most frequent genetic lesions in B-ALL, PAX5 alterations have been demonstrated to impair B cell differentiation and give rise to overt leukemia with the acquisition of cooperating genetic lesions." (PMID 36387144, 2022). "One of the leukemias harbored additional deletions in PAX5 and IKZF1, thus can be classified as IKAROS plus similar to the spontaneous leukemia that was developed after IL7RAins transduction." (PMID 35115489, 2022). "Comparing to PAX5::ETV6, PAX5::ELN acts as a more potent initiating event to induce leukemia, with frequent acquisition of secondary mutations in Ptpn11, Jak3, and Kras genes in mice." (PMID 36387144, 2022). "Both the DNA‐binding function and kinase activity of Pax5‐Jak2 were contributing to leukemia development." (PMID 35156727, 2022). "In preleukemic mice, conditional Pax5 deletion cooperated with E2A-PBX1, leading to an increased leukemia penetrance and shortening its latency, hence confirming a tumor-suppressive role for Pax5 in an E2A-PBX1 background." (PMID 35886910, 2022). "Specifically, we will describe the most prevalent roles of PAX5 in vital biological processes (e.g., B-cell maturation) and neoplasia (e.g., leukemia and lymphoma) upon its aberrant expression." (PMID 36077495, 2022). "Clinically, the high specificity and sensitivity of the PAX5 transcription factor have made it a useful marker in identifying and distinguishing lymphomas and leukemias of B-cell origin." (PMID 36077495, 2022). "The DNA‐binding function and kinase activity of Pax5‐Jak2 as well as IL‐7 signaling contributed to leukemia development." (PMID 35156727, 2022). "In summary, these data indicate that the DNA‐binding activity of Pax5‐Jak2 contributes to leukemia development." (PMID 35156727, 2022). "Remarkably, even brief Pax5 restoration in B-ALL cells causes rapid cell cycle exit and disables their leukemia-initiating capacity." (PMID 36387144, 2022).